TM4SF19-DYNLT2B (TM4SF19-DYNLT2B readthrough (NMD candidate))
Synonyms: formerly TM4SF19-TCTEX1D2
Gene: Protein-coding gene on chromosome 3 (196,316,082 to 196,338,373, reverse strand). Ensembl gene ENSG00000273331.
Genetic constraint (gnomAD): Missense variants: 216 observed, 265.2 expected, observed/expected ratio (o/e) 0.81, 90% interval 0.73 to 0.91. Synonymous variants: 107 observed, 112.54 expected, observed/expected ratio (o/e) 0.95, 90% interval 0.81 to 1.12.